PSG7 (pregnancy specific beta-1-glycoprotein 7)
Synonyms: PS-beta-G-7; PSBG-7; PSGGA
Tractability: Antibody: UniProt places it where antibodies can reach, with high confidence; UniProt predicts a signal peptide or a membrane-spanning region; its Gene Ontology location is reachable by antibodies, with medium confidence.
Gene: Protein-coding gene on chromosome 19 (42,924,132 to 42,937,207, reverse strand). Ensembl gene ENSG00000221878.
Subcellular location: Secreted
Pathways (Reactome):
Hemostasis: Cell surface interactions at the vascular wall
Gene Ontology:
Molecular function: protein binding
Biological process: female pregnancy
Cellular component: extracellular region
Genetic constraint (gnomAD): Loss-of-function variants: 55 observed, 43.44 expected, observed/expected ratio (o/e) 1.27, 90% interval 1.02 to 1.59. The synonymous counts are far from expectation, so gnomAD's model fits this gene poorly and the ratio says little. Missense variants: 790 observed, 509.57 expected, observed/expected ratio (o/e) 1.55, 90% interval 1.46 to 1.64. Synonymous variants: 296 observed, 194.5 expected, observed/expected ratio (o/e) 1.52, 90% interval 1.38 to 1.68.
Homologues: Orthologues: chimpanzee PSG7 (96% identical). Paralogues in human: PSG8 (90% identical), PSG3 (90% identical), PSG4 (90% identical), PSG1 (89% identical), PSG6 (89% identical), PSG9 (85% identical), PSG5 (68% identical), PSG2 (68% identical), PSG11 (67% identical), CEACAM1 (42% identical), CEACAM5 (39% identical), CEACAM6 (37% identical), and 12 more.
Diseases named in the same sentence as PSG7 in open-access papers:
PSG7 is named in the same sentence as 9 diseases in open-access papers, as found by Europe PMC text mining. Sharing a sentence is not in itself a finding about the gene and the disease. The quoted sentences say what the papers report.
preeclampsia (2 papers, 2024 to 2025). Preeclampsia is a hypertensive disorder of pregnancy that is characterized by new-onset hypertension with proteinuria presenting after 20 weeks of gestation, and depending on mild or severe forms may initially present with severe headache, visual disturbances, and hyperreflexia. "Previous clinical cohort studies have implicated increased levels of circulating PSG7 and PSG9 with preeclampsia." (PMID 40991151, 2025). "Our MR findings reported a similar direction of effect with PSG7 having a nominally significant p-value for preeclampsia (p = 0.0345)." (PMID 40991151, 2025). "Although differences in levels of PSG7, PSG9 and PSG1 proteins (all encoded by polymorphic pseudogenes) have been proposed as biomarkers for preeclampsia, no information regarding the individual genetic variability of these genes was provided in these studies." (PMID 39488654, 2024).
gastric cancer (1 paper, 2022). A primary or metastatic malignant neoplasm involving the stomach. "As the fifth member of the PSG family detected in the fetal liver (Khan and Hammarström, 1990), PSG7 was expected to interact with the prognostic lncRNAs (CTD-2218G20.2) in gastric cancer, but the actual mechanism remains elusive." (PMID 36276966, 2022).
head and neck squamous cell carcinoma (1 paper, 2021). A squamous cell carcinoma that arises from any of the following anatomic sites: lip and oral cavity, nasal cavity, paranasal sinuses, pharynx, larynx, and salivary glands. "The top-ranked somatic eQTL genes with truncations include OR8D1 in LUSC, SOX10 in head and neck squamous cell carcinoma (HNSC), and PSG7 in kidney renal clear cell carcinoma (KIRC)." (PMID 33691015, 2021).
kidney cancer (1 paper, 2025). Primary or metastatic malignant neoplasm involving the kidney. "The signature of PSG3, PSG7, and PSG8 was also found to show a statistically significant survival difference (P = .0138) between the PSG+ and PSG− groups in uterine cancer and borderline significance (P = .0746) in female kidney cancer patients." (PMID 40257008, 2025).
cancer (3 papers, 2020 to 2025). A tumor composed of atypical neoplastic, often pleomorphic cells that invade other tissues. "Specifically, CTD-2218G20.2 was predicted to interact with 86 proteins (Pearson correlation coefficient, PCC > 0.3), some of which, including PSG4, PSG5, and PSG7, could also interact with cancer-related proteins, including KISS1, TIMP2, MMP11, IGFBP1, EGFR, and CDKN1C." (PMID 32117443, 2020). "We then asked if this pattern (a statistically significant alteration of the ‘KRAS Signaling Down’ pathway between the PSG+ and PSG− groups in female LUAD patients grouped by the signature of PSG3, PSG7, and PSG8) is present in other TCGA cancer datasets." (PMID 40257008, 2025). "The signature of PSG3, PSG7, and PSG8 was further assessed for female patients in other TCGA cancer datasets." (PMID 40257008, 2025). "CEA has been extensively studied and used as a cancer marker, whereas PSG, especially PSG7, has been relatively poorly studied in the field of oncology." (PMID 36276966, 2022). "Specifically, pregnancy-specific glycoproteins, including PSG4, PSG5, and PSG7, were those proteins jointly interacting with CTD-2218G20.2 and cancer-related proteins, which were highly correlated with CTD-2218G20.2 (PCC > 0.3)." (PMID 32117443, 2020).
tumor (2 papers, 2022 to 2025). "PSG7 is the only key gene highly expressed in both PTC tumor tissues from TCGA and GEO compared with healthy tissues." (PMID 36276966, 2022). "Of the six genes (IGF2BP1, GPRC6A, IL37, CRCT1, SEMG1, and PSG7) for which we analyzed the differential expression between tumor tissues and healthy tissues in TCGA, four genes (CRCT1, PSG7, IL37, and IGF2BP1) showed notable differences." (PMID 36276966, 2022). "Accordingly, it is reasonable to infer that PSG7 may play a pivotal role in PTC progression by altering the tumor immune microenvironment with increasing age." (PMID 36276966, 2022). "PSG7 was remarkably correlated with clinicopathological parameters (pathologic stage, T stage, and N stage) of PTC patients, and PSG7 expression was elevated in tumor samples from both TCGA and the Gene Expression Omnibus and was strongly associated with progressive stage and poor prognosis." (PMID 36276966, 2022). "In addition, the reshaped tumor immune microenvironment participated in PTC development in the PSG7 high-expression group." (PMID 36276966, 2022). "The PSG3 gene had the highest expression level in both male and female tumor samples whereas PSG2, PSG7, and PSG11 had relatively lower expression levels." (PMID 40257008, 2025). "Note that a tumor sample in which PSG3, PSG7, and PSG8 had no expression was defined as PSG− and otherwise was defined as PSG+." (PMID 40257008, 2025).
PSG7 also shares sentences with these, for which no sentence is quoted: Miscarriage (1 paper); papillary thyroid carcinoma (1); uterine cancer (1).